CASC17 (cancer susceptibility 17)
Synonyms: LINC00600
Gene: Long non-coding RNA gene on chromosome 17 (71,097,774 to 71,202,203, reverse strand). Ensembl gene ENSG00000260785.
Diseases named in the same sentence as CASC17 in open-access papers:
CASC17 is named in the same sentence as 7 diseases in open-access papers, as found by Europe PMC text mining. Sharing a sentence is not in itself a finding about the gene and the disease. The quoted sentences say what the papers report.
dementia (1 paper, 2020). Loss of intellectual abilities interfering with an individual's social and occupational functions. "However, interestingly, several previous GWAS have identified SNPs in CASC17 associated with the risk of psychosis and impulsive behavior, which are characteristic features of dementia in PD." (PMID 33613413, 2020).
cancer (2 papers, 2015 to 2023). A tumor composed of atypical neoplastic, often pleomorphic cells that invade other tissues. "However, the human non-protein coding gene CASC17 (“cancer susceptibility candidate 17”) was located to this region." (PMID 25955013, 2015).
CASC17 also shares sentences with these, for which no sentence is quoted: Cognitive impairment (2 papers); cognitive decline (1); gout (1); male pattern baldness (1); psychosis (1).